CCL5 (C-C motif chemokine ligand 5)
Diseases named in the same sentence as CCL5 in open-access papers (continued):
Sharing a sentence is not in itself a finding about the gene and the disease.
acute coronary syndrome (10 papers, 2011 to 2024). Signs and symptoms related to acute ischemia of the myocardium secondary to coronary artery disease. "A significant correlation has been demonstrated between chemokine (C-C motif) ligand 5 (CCL5), also known as regulated on activation, normal T cell expressed and secreted (RANTES), IL-1β level, and mortality risk in patients with acute coronary syndromes." (PMID 35268485, 2022). "The aim of this study was to investigate the prognostic importance of chemokines CCL3/MIP-1α, CCL5/RANTES and CCL18/PARC for the risk of future cardiovascular events in patients with acute coronary syndromes (ACS)." (PMID 23029252, 2012). "Third, CCL5 bound to heparan sulfate in the vessel wall may be released as the use of heparin is quite common in patients with acute coronary syndrome." (PMID 38899522, 2024). "Notably, chemokines CCL3, CCL5 and CCL18 were identified as the risk factors of short-term mortality in patients with acute coronary syndromes." (PMID 36231033, 2022). "Additionally, the use of heparin in acute coronary syndrome might lead to increased CCL5 levels due to the release of heparin sulfate-bound chemokines in the vessel wall." (PMID 26688689, 2015). "Hazard Ratios (95% confidence intervals) for a fatal future cardiovascular event during follow-up in patients with the acute coronary syndrome, according to baseline levels of CCL3/MIP-1α, CCL5/RANTES and CCL18/PARC, Bad Nauheim ACS II registry." (PMID 23029252, 2012).
clear cell renal cell carcinoma (10 papers, 2020 to 2025). "In clear cell renal cell carcinoma (ccRCC), METTL14 expression is inversely correlated with Treg abundance and positively associated with CCL5 levels, suggesting a METTL14/CCL5/Tregs axis that shapes the tumor immune landscape." (PMID 41164187, 2025). "In the cancer genome atlas (TCGA) database, compared to the adjacent normal tissue, CCL5 was highly expressed in clear cell renal carcinoma tissue, and patients with high CCL5 expression in renal cancer were closely related to poor prognosis." (PMID 39227943, 2024). "CCL5 educated macrophages toward TAMs, which reciprocally enhanced clear cell renal cell carcinoma progression via CCL5/CCR5 and activated STAT3/SOX17low/YAP." (PMID 37759462, 2023). "Through multiple verification of bioinformatics and experiments, CCL5 was identified as a potential biomarker and target for clear cell renal cell carcinoma immunotherapy." (PMID 32081834, 2020). "In clear cell renal cell carcinoma (CCRCC), both an increase in CCL5+ MΦs and a positive correlation between ST3G5 expression and poor survival have been reported." (PMID 37716915, 2024). "Analysis of The Cancer Genome Atlas (TCGA) kidney clear cell carcinoma (KIRC) database for RNA sequencing data related to ccRCC showed significantly reduced overall survival in high expressers of CXCL8 (IL8), CCL5, CSF2, TFPI-2, and SERPINE1 (PAI1)." (PMID 35886951, 2022).
Crohn disease (10 papers, 2013 to 2024). A gastrointestinal disorder characterized by chronic inflammation involving all layers of the intestinal wall, noncaseating granulomas affecting the intestinal wall and regional lymph nodes, and transmural fibrosis. "A previous study demonstrated that Debaryomyces dominated in inflamed mucosal tissues of Crohn’s disease and impaired mucosal healing via myeloid-type I interferon–CCL5 axis." (PMID 35281451, 2022). "In addition, granuloma cells in intestinal tissues from patients with Crohn's disease express CCL5." (PMID 25566510, 2014).
Hepatic steatosis (10 papers, 2012 to 2025). Steatosis is a term used to denote lipid accumulation within hepatocytes. "Since the processes of hepatic lipogenesis and lipid uptake were altered in obese CCL5 deficient mice, these processes may account for severe hepatic steatosis caused by CCL5 deficiency." (PMID 36713454, 2022). "In vitro, lipid-overloaded hepatocytes were shown to produce CCL5, which activated the fibrogenic activity of immortalized primary human HSCs (LX-2), and, vice versa, activated HSCs secreted CCL5, which deteriorated hepatic steatosis." (PMID 40794228, 2025). "In contrast, CCL5 KO mice were more insulin resistant and had severe hepatic steatosis than WT mice under obese conditions." (PMID 36713454, 2022). "Our result suggests that in early NASH, HSCs secrete Ccl5 which contributes to a broad array of mechanisms by which hepatic steatosis and inflammation are achieved." (PMID 29760499, 2018). "Maraviroc, a CCL5/RANTES inhibitor, ameliorated hepatic steatosis in a high-fat diet (HFD)-induced model of NAFLD." (PMID 31849997, 2019).
ischemia (10 papers, 2016 to 2024). A hypoperfusion of the BLOOD through an organ or tissue caused by a PATHOLOGIC CONSTRICTION or obstruction of its BLOOD VESSELS, or an absence of BLOOD CIRCULATION. "This study investigated the role of Chemokine (C-C motif) ligand 5 (CCL5) as a key mediator of hepatic ischemia–reperfusion injuries (IRI), which are common postoperative hepatic complications." (PMID 28623253, 2017). "CXCL4-CCL5 enhances the effect of CCL5, which contributes to ischemia-induced inflammation and brain injury, against which a CXCL4/CCL5 inhibitor protects." (PMID 28936196, 2017).
leukemia (10 papers, 2000 to 2025). A malignant (clonal) hematologic disorder, involving hematopoietic stem cells and characterized by the presence of primitive or atypical myeloid or lymphoid cells in the bone marrow and the blood. "In hepatic LAMs, the majority of M1-associated genes, including CCL5, CXCL1, IL-12β, iNOS, and TNF-α, exhibit increased expression during leukemia progression." (PMID 38779660, 2024). "Induces apoptosis in leukemia cells by activating caspase-3; reduces chemokines (CCL2, CCL5), promoting apoptosis and cytokine regulation." (PMID 40003268, 2025). "CML red pulp macrophages (RPMs) are able to produce a variety of cytokines and chemokines such as IL-10, CCL3, CCL4, CCL5, CXCL1, TNF-α, and SCF, to sustain leukemia initial cells (LICs)." (PMID 38779660, 2024). "Overexpression of human FST317 and FST344 isoforms enhanced clonogenicity and leukemia engraftment in xenotransplantation model via RET,IL2RA, and CCL5 upregulation." (PMID 32134197, 2020). "FST upregulated expression of RET, IL2RA, and CCL5 that collectively potentiated MAPK signaling and promoted leukemia growth in vitro and in vivo." (PMID 32134197, 2020).
mastitis (10 papers, 2016 to 2025). Inflammation of breast tissue during lactation or postpartum due to an obstructed duct or infection. "1,25(OH)2D3 induces localized expression of NOS2 in milk CD14+ cells and increased CCL5 in CD14- cells during experimentally induced mastitis caused by S. uberis." (PMID 36144467, 2022). "Moreover, CCL5 has also been reported to be closely associated with the pathogenesis of chronic mammary inflammation and mastitis." (PMID 36336691, 2022). "The CCL5 gene has been found to be up-regulated in bovine mammary epithelial cells stimulated by E. coli, but down-regulated in mammary glands with S. aureus-induced mastitis." (PMID 36336691, 2022). "Additionally, many other immunity and inflammatory associated genes, such as SAA3, CCL5, C3 and CSF3, were also documented in mastitis-infected mammary glands." (PMID 32927884, 2020). "The CCL5 chemokine has been shown to play a role in the inflammatory response to bovine respiratory syncytial virus, Alcelaphine herpesvirus 1, mastitis, bovine tuberculosis and parasitic protozoan infections with Toxoplasma gondii, Neospora canium and Eimera bovis." (PMID 27479136, 2016). "DEGS such as IL10, CCL5, IL1B, OSM, TNFRSF1B, IL7, and CCR3, among others, implicated in these pathways, may play a crucial role in the development of subclinical mastitis in Bactrian camels, though further analysis is needed to explore their potential functions." (PMID 40005880, 2025). "Similarly, the high expression of CCl5 has also reported in E. coli-induced mastitis in BMECs." (PMID 32927884, 2020). "Levels of IFN-γ, IL-4, TNF-α, MYD88, CCL5, TLR4, TLR9, LTF, PRLR, Keap1 and OXSR1 genes expression were significantly up-regulated in ewes affected with mastitis than resistant ones." (PMID 40542007, 2025). "Mastitis-affected ewes had considerably higher levels of IFN-γ, IL-4, TNF-α, MYD88, CCL5, TLR4, TLR9, LTF, and PRLR gene expression than resistant ones." (PMID 40542007, 2025). "In a similar study, treatment of mammary gland with 25(OH)D3 in cattle with LPS induced mastitis showed total milk somatic cells having upregulated expression of NOS2, RANTES/CCL5, DEFB3, DEFB4, DEFB7, DEFB10, IL1B, and IL8, with most effects being observed between 4–8 h following treatment." (PMID 36144467, 2022). "Besides, CCL3, CCL4, CCL5 and CCL20 have also been reported as differentially expressed in response to mastitis by other investigators." (PMID 36336691, 2022). "In addition, the high expression of CXCL10, CCL2, CCL5 and CCL20 was noticed in bovine mammary epithelial cells in E. coli induced mastitis, which is essential for the recruitment of leucocytes." (PMID 32927884, 2020). "In the current investigation, qRT-PCR was used to measure the levels of antioxidant (CAT, GPX1, Keap1, OXSR1, ATOX1, GST, and Nrf2) and immune (IFN-γ, IL-4, TNF-α, MYD88, CCL5, TLR4, TLR9, LTF, and PRLR) genes in Barki ewes that were resistant and non-resistant to mastitis." (PMID 40542007, 2025).
parasitemia (10 papers, 2009 to 2024). "In addition to strong expression of IFNβ and CCL5 in all cell types, parasite infection induces the expression of genes involved in cell-matrix interactions (osteopontin; SPP1) carbohydrate modification (B4GT5 and B3GNT2), vesicular transport SYTL3 and T-SNARE1 and Ca2+ homeostasis STIM1 and CARKL." (PMID 19480704, 2009). "Eotaxin was positively correlated with NE and plasma RANTES (CCL5), IL-1α, and IL-2, and strongly negatively correlated with MPO, Mcpt1, parasitemia, plasma IL-4, ileal MCs, and FITC-dextran." (PMID 38780542, 2024). "Serum levels of IL-6, IL-27, CCL3, CCL5, CXCL10, CCL11, and CCL17 in patients with different parasitic infection profiles living in the rural community of Brejo do Amparo, Januária, Minas Gerais, Brazil." (PMID 33777015, 2021). "Of note, the perturbation of the liver damage parameters ALT, AST, total bilirubin, and also MDP values of IL-4, IL-6, IL-8, IL-12p70, CXCL9, CCL5, CCL2, CRP, fibrinogen and parasitemia levels showed an inverse correlation with the time living in the endemic area." (PMID 34727121, 2021).
schizophrenia (10 papers, 2010 to 2025). A major psychotic disorder characterized by abnormalities in the perception or expression of reality. "It is thought to be produced by neurons, oligodendrocytes, astrocytes and microglia, and, apart from a role in neuroinflammation, evidence that CCL5 can modulate synaptic glutamate release may be particularly relevant to schizophrenia risk." (PMID 30691477, 2019). "Altered peripheral CCL5 levels have been detected in patients with schizophrenia, which is of interest considering the data presented here, and the genetic association between schizophrenia and JNK pathway genes." (PMID 30691477, 2019). "The present study compares the serum levels of selected cytokines and chemokines—IL-17, IL-22, IL-23, IL-8, IL-21, CCL20, CXCL10, CCL2and CCL5—in schizophrenia patients to healthy controls due to growing evidence linking immune-inflammatory and metabolic dysregulation to schizophrenia." (PMID 41200225, 2025). "Besides categories related to hematological function, the Tan schizophrenia module was also enriched for the Neurological Disease category (CCL5, PRKCQ, PTAFR, AKR1B1, CD247, IL10RA and KHSRP)." (PMID 22761806, 2012). "This study aimed to examine serum levels of Th17-related cytokines (IL-17, IL-21, IL-22, IL-23) and chemokines (CCL2, CCL5, CCL20, CXCL10, IL-8) in schizophrenia patients compared to healthy controls and to explore their associations with symptom severity and laboratory parameters." (PMID 41200225, 2025).
skin inflammation (10 papers, 2010 to 2024). "Dermatitis lesions in hK14mIL33tg mice were associated with a substantial increase in the concentration of IL-13, IL-5, RANTES/CCL5 and Eotoxin 1/CCL11, whereas the levels of TSLP, IFN-γ and TNF-α were not altered." (PMID 25427661, 2014). "An important reduction of MPO activity was observed in a T-cells dependent model of skin inflammation (DNFB-induced CHS) by [44AANA47]-CCL5 at 1 mg/kg (46.6% (53.4% of vehicle)." (PMID 20090949, 2010). "In fact, both in ICD, that results in activation of innate immune response with infiltration in the ear of mainly neutrophils and macrophages, and in CHS, which is instead a T cell dependent model of skin inflammation, Met-CCL5 showed a therapeutic efficacy by reducing swelling by 50%." (PMID 20090949, 2010). "The miRNA precursor miR-146a can inhibit chronic skin inflammation by decreasing the expression levels of IFN-γ, CCL5, and CCL8 in the skin." (PMID 30459600, 2018). "To test the importance of several of these molecules in TWEAK-mediated skin inflammation, we blocked CCL2, CCL5 and CCL7 together, by injecting neutralizing antibodies at the time of rTWEAK injection." (PMID 28530223, 2017). "In this study we tested two CCL5 antagonists in two models of contact skin reaction, ICD and CHS, to demonstrate that blocking the receptor or the ligand are both effective strategies to inhibit skin inflammation." (PMID 20090949, 2010).
steatosis (10 papers, 2018 to 2025). Increased lipid within the cytoplasm of cells. "To test this hypothesis, we investigated whether Ccl5 directly causes steatosis in hepatocytes or is simply an upregulated gene with an unrelated function." (PMID 29760499, 2018). "To further investigate whether CCL5 directly acts on lipid metabolism in hepatocytes, we examined the effect of CCL5 on hepatocyte steatosis in vitro." (PMID 36713454, 2022). "Furthermore, Ccl5 directly induces steatosis and pro-inflammatory factors in healthy hepatocytes through the receptor Ccr5." (PMID 29760499, 2018). "To test whether Ccl5 expressed by HSCs signal through Ccr5 on hepatocytes to induce steatosis and to upregulate pro-inflammatory cytokines, we applied both recombinant Ccl5 and the Ccr5-specific inhibitor Maraviroc on hepatocytes." (PMID 29760499, 2018). "Besides, chemokines such as monocyte chemoattractant protein 1 (MCP-1)/CCL2, RANTES/CCL5, and other CXC chemokines have gained special importance in the progression of NAFL to NASH by regulating insulin resistance and steatosis via the inflammatory crosstalk between liver and adipose tissue." (PMID 33603757, 2020).
vitiligo (10 papers, 2017 to 2025). Generalized well circumscribed patches of leukoderma that are generally distributed over symmetric body locations and is due to autoimmune destruction of melanocytes. "3/5 studies (266 patients versus 111 controls) reported significantly increased CCL5 concentrations in the circulation of vitiligo patients compared to healthy controls." (PMID 36911664, 2023). "Stressed melanocytes release CXCL12 and CCL5, which are mediated in T-cell homing to the skin in vitiligo." (PMID 34970551, 2021). "show that CXCL12 and CCL5 are relevant to the recruitment of APCs in early vitiligo." (PMID 29238346, 2017). "In dogs, we found enrichment of T cell gene signatures, with upregulation of IFNG, TNF, PRF1, IL15, CTSW, CXCL10, and CCL5 in both VKH and vitiligo in dogs compared to healthy controls." (PMID 33384688, 2020). "We found significant upregulation of CCL5 and CXCL10, as well as CXCL7 (gene name PPBP) in canine VKH and vitiligo." (PMID 33384688, 2020). "Mouse and human studies have shown that the chemokines CCL5 and CXCL10 are expressed in the skin during vitiligo." (PMID 33384688, 2020). "From the studied chemokines, only CCL5 (p < 0.05) and CXCL10 (p < 0.001) were significantly upregulated in vitiligo lesional skin compared with healthy control skin." (PMID 30515176, 2018). "In addition, the authors found that CCL5/CCR5 axis functioned as a chemokine circuit between effector T cells and Tregs in vitiligo patients." (PMID 38937380, 2024). "Several studies demonstrate reduced levels of CCL5/CCR4, CCL22, CCL21, and CCR6 in vitiligo skin, which could explain the failure of circulating Tregs to localize to the skin, thus suggesting that the modulating expression of these chemokines may be potential therapeutic targets in vitiligo." (PMID 36675037, 2023).
acute kidney injury (9 papers, 2011 to 2025). Sudden and sustained deterioration of the kidney function characterized by decreased glomerular filtration rate, increased serum creatinine or oliguria. "CXCL2, CCL5, and TNFα were also reduced in HuSAP+ mice (relative to WT) 48 hours after Stx2 treatment and therefore may be crucial for the inflammatory pathology leading to acute renal failure." (PMID 21731756, 2011).
bronchiolitis (9 papers, 2016 to 2025). Inflammation of the bronchioles characterized by swelling of the bronchioles and mucus accumulation. "Therein, the authors found a single SNP in CCL5 (rs2107538*CT), exhibiting an association with hRSV-bronchiolitis and also with the need for mechanical ventilation." (PMID 30936869, 2019). "Furthermore, SNPs in Toll-like receptors (TLRs), including rs4986790*TLR4, rs1898830*TLR2, rs7656411*TLR2, rs352162*TLR9, and rs187084*TLR9 as well as rs2280788*CCL5 were associated with severity of bronchiolitis." (PMID 32375305, 2020). "The authors observed that the SNP rs2107538*CCL5 was associated with bronchiolitis caused by respiratory syncytial virus (RSV) and RSV-subtype-A while the SNP rs1060826*NOS2 was associated with bronchiolitis caused by rhinovirus, indicating viral-specific polymorphisms." (PMID 32375305, 2020). "Measurements by NS demonstrated that relative to both RSV− bronchiolitis and healthy control subjects, RSV+ bronchiolitis was associated with higher levels of IFN-γ, IL-1β, CCL5/RANTES, and IL-10 (respectively) (P < .05 throughout)." (PMID 28368490, 2017). "Nasosorption (but not NPA) levels of interferon γ, interleukin 1β, CCL5/RANTES, and interleukin 10 (IL-10) were elevated in RSV+ bronchiolitis (all P < .05), furthermore CCL5 and IL-10 correlated with RSV load (P < .05)." (PMID 28368490, 2017). "In nasosorption samples collected from RSV-infected infants, a decreased IFN-γ and CCL5/RANTES expression coupled with exaggerated IL-17 expression and mucogenesis were markers of more severe bronchiolitis." (PMID 35406717, 2022).
diabetic nephropathy (9 papers, 2019 to 2024). "ALPK1 is a mediator of CCL2 and CCL5 chemokine, and upregulation of NF-κβ is associated with the induction of diabetic nephropathy." (PMID 36139553, 2022). "In streptozotocin-treated mice, which is a rodent model for insulin deficient type 1 diabetes, high glucose increased the expression of renal CCL2 and CCL5, which was associated with the induction of diabetic nephropathy." (PMID 33207809, 2020). "The results showed that both CCL5 and CXCL1 were upregulated in diabetic nephropathy patients and were associated with a decline in renal function." (PMID 37189669, 2023). "ALPK1 is a mediator for CCL2 and CCL5 chemokine up‐regulation involving in diabetic nephropathies induction." (PMID 31557402, 2019). "Our data suggest that ALPK1 is a potential mediator for CCL2 and CCL5 chemokines induction involving in ALPK1‐mediated accelerated diabetic nephropathies." (PMID 31557402, 2019). "ALPK1 was therefore determined to be a mediator involved in diabetic-nephropathy-induced upregulation of CCL2 and CCL5 chemokines." (PMID 36139553, 2022).